LINC01798 (long independently transcribed non-coding RNA 1798)
Synonyms: LINC01799
Gene: Long non-coding RNA gene on chromosome 2 (66,574,014 to 67,005,271, forward strand). Ensembl gene ENSG00000232046.
Diseases named in the same sentence as LINC01798 in open-access papers:
LINC01798 is named in the same sentence as 2 diseases in open-access papers, as found by Europe PMC text mining. Sharing a sentence is not in itself a finding about the gene and the disease. The quoted sentences say what the papers report.
lung adenocarcinoma (1 paper, 2024). A carcinoma that arises from the lung and is characterized by the presence of malignant glandular epithelial cells. "In the latest literature, LINC01798/miR-17-5p axis improved the prognosis of patients with lung adenocarcinoma, and miR-17-5p level decreased after transfection of pcDNA3.1-LINC01798." (PMID 38627627, 2024).
LINC01798 also shares sentences with these, for which no sentence is quoted: COVID-19 (1 paper).